HDDC2 (HD domain containing 2)
Description:
Catalyzes the dephosphorylation of the nucleoside 5'-monophosphates deoxyadenosine monophosphate (dAMP), deoxycytidine monophosphate (dCMP), deoxyguanosine monophosphate (dGMP) and deoxythymidine monophosphate (dTMP).
Synonyms: C6orf74; NS5ATP2; CGI-130; dJ167O5.2
Tractability: PROTAC: ubiquitination databases record sites on it; its protein half-life has been measured.
Gene: Protein-coding gene on chromosome 6 (125,219,962 to 125,302,128, reverse strand). Ensembl gene ENSG00000111906.
Subcellular location (Human Protein Atlas): Nucleoli; Nucleoplasm
Gene Ontology:
Molecular function: protein binding; 5'-deoxynucleotidase activity
Biological process: deoxyribonucleoside monophosphate catabolic process
Cellular component: cytoplasm
Genetic constraint (gnomAD): Loss-of-function variants: 19 observed, 19.6 expected, observed/expected ratio (o/e) 0.97, 90% interval 0.68 to 1.42. The upper end of that interval is the gene's LOEUF score, 1.42, which puts it in group 5 of 6, group 1 being the genes least tolerant of losing a copy. Missense variants: 239 observed, 221.42 expected, observed/expected ratio (o/e) 1.08, 90% interval 0.97 to 1.2. Synonymous variants: 98 observed, 77.49 expected, observed/expected ratio (o/e) 1.26, 90% interval 1.07 to 1.5.
Homologues: Orthologues: chimpanzee HDDC2 (97% identical), macaque HDDC2 (89% identical), pig HDDC2 (89% identical), rabbit HDDC2 (89% identical), mouse Hddc2 (87% identical), dog HDDC2 (85% identical), guinea pig HDDC2 (81% identical), rat Hddc2 (76% identical), tropical clawed frog hddc2 (72% identical), zebrafish hddc2 (61% identical), Drosophila melanogaster CG11050 (44% identical), Caenorhabditis elegans F45F2.9 (36% identical).
Diseases named in the same sentence as HDDC2 in open-access papers:
HDDC2 is named in the same sentence as 2 diseases in open-access papers, as found by Europe PMC text mining. Sharing a sentence is not in itself a finding about the gene and the disease. The quoted sentences say what the papers report.
glioma (1 paper, 2024). A benign or malignant brain and spinal cord tumor that arises from glial cells (astrocytes, oligodendrocytes, ependymal cells). "Moreover, DUSP11, LPIN3, MTMR11, HDDC2, and PLPPR3 have not been queried for glioma-related studies." (PMID 39830513, 2024).
HDDC2 also shares sentences with these, for which no sentence is quoted: hepatocellular carcinoma (1 paper).